ITGB4 (integrin subunit beta 4)
Diseases named in the same sentence as ITGB4 in open-access papers (continued):
Sharing a sentence is not in itself a finding about the gene and the disease.
esophageal cancer (2 papers, 2022 to 2024). A primary or metastatic malignant neoplasm involving the esophagus. "Esophageal carcinoma TCGA data revealed that, the expression of ITGB4 in esophageal carcinoma tissue was apparently higher than that in normal esophageal tissue." (PMID 38831335, 2024). "At the same time, the expression of NEDD4L was negatively correlated with ITGB4 expression in esophageal carcinoma." (PMID 38831335, 2024). "According to immunohistochemistry analysis on 96 pairs of surgical tissues from esophageal carcinoma patients, the ITGB4 expression increased with the increase in esophageal carcinoma stage and grade." (PMID 38831335, 2024). "In this study, ITGB4 was related to the poor prognosis of esophageal carcinoma." (PMID 38831335, 2024). "Mechanically, the HECT domain of NEDD4L specifically binds to the Galx-β domain of ITGB4, which modifies the K915 site of ITGB4 through ubiquitination, and promotes the ubiquitination degradation of ITGB4, thus suppressing the malignant phenotype of esophageal carcinoma." (PMID 38831335, 2024). "Moreover, we observed the effect of NEDD4L-mediated ubiquitination degradation of ITGB4 on the survival of mice by suppressing the metastasis of esophageal carcinoma." (PMID 38831335, 2024). "Similarly, the esophageal carcinoma metastasis model also suggested that, after restoring ITGB4 expression, NEDD4L lost its suppression on the metastasis of esophageal carcinoma." (PMID 38831335, 2024). "In terms of the mechanism, the HECT domain of NEDD4L specifically bound to the Galx-β domain of ITGB4, which modified the K915 site of ITGB4 in an ubiquitination manner, and promoted the ubiquitination degradation of ITGB4, thus suppressing the malignant phenotype of esophageal carcinoma." (PMID 38831335, 2024). "Mechanically, the HECT domain of NEDD4L specifically bound to the Galx-β domain of ITGB4, which modified the K915 site of ITGB4 in an ubiquitination manner, and promoted the ubiquitination degradation of ITGB4, thus suppressing the malignant phenotype of esophageal carcinoma." (PMID 38831335, 2024). "Finally, the protein ITGB4, which was related to esophageal carcinoma progression and could be degraded by NEDD4L through ubiquitination, was screened." (PMID 38831335, 2024). "Subsequently, based on the bioinformatics platform UbiBrowser, the esophageal carcinoma TCGA database and GEO database (GSE53625), we screened the ITGB4 protein, which was related to the progression of esophageal carcinoma, and could be degraded by NEDD4L-mediated ubiquitination." (PMID 38831335, 2024). "In the subcutaneous esophageal carcinoma tumor bearing model and 96 pairs of surgical tissue samples from esophageal carcinoma patients, immunohistochemistry analysis further verified that NEDD4L was negatively correlated with ITGB4 expression." (PMID 38831335, 2024). "Our results suggested that, high NEDD4L expression markedly prolonged the survival of mice, while after reversing ITGB4 expression, NEDD4L lost its function in extending the survival of mice with esophageal carcinoma lung metastasis." (PMID 38831335, 2024). "While after restoring ITGB4 expression, NEDD4L lost its suppression on the growth of esophageal carcinoma." (PMID 38831335, 2024).
invasive carcinoma (2 papers, 2007 to 2021). A carcinoma that is not confined to the epithelium, and has spread to the surrounding stroma. "ITGB4, a member of the integrin family, mediates cell-cell adhesion or cell growth and plays a significant role in the biology of invasive carcinoma by associating with integrin alpha 6 (ITGA6) subunit." (PMID 34745421, 2021).
keratoconus (2 papers, 2023). A degenerative, structural disorder of the eye, characterized by a cone-shaped protrusion of the cornea. "The mutant form of miR-184 fails the competition role of wild-type miR-184 with miR-205 for targeting the 3′UTRs of INPPL1 and ITGB4 and contributes to familial keratoconus with cataracts." (PMID 38174044, 2023).
leukemia (2 papers, 2012 to 2013). A malignant (clonal) hematologic disorder, involving hematopoietic stem cells and characterized by the presence of primitive or atypical myeloid or lymphoid cells in the bone marrow and the blood. "ITGB1, ITGB3, ITGA4, and ITGA5 were expressed in five of the six leukemia cell lines, and ITGB4 and ITGA6 were specifically expressed in the three EVI1high leukemia cell lines." (PMID 22295105, 2012). "Because similar results were also obtained using the anti-cancer drug, VP-16, the treatment with anti-ITGA6 or anti-ITGB4 antibodies or anti-cancer drugs might recover the drug-sensitivity of EVI1high leukemia cells." (PMID 22295105, 2012). "Moreover, treating EVI1high leukemia cells with neutralizing antibodies against ITGA6 or ITGB4 resulted in an enhanced responsiveness to anti-cancer drugs and a reduction of their cell adhesion ability." (PMID 22295105, 2012). "The downregulation of EVI1 or ITGB4 in UCSD/AML1 leukemia cells restored chemo-sensitivity." (PMID 22295105, 2012). "As a corollary, the increased expression of the ITGA6/ITGB4 complex in EVI1high leukemia might be an important factor in maintaining leukemia stem cells in the bone marrow." (PMID 22295105, 2012). "Therefore, the expression of ITGA6 and ITGB4 was EVI1 dependent, and the increased expression of ITGA6 and ITGB4 in EVI1high leukemia cells increased their ability to adhere to the osteoblastic MC3T3-E1 cell line." (PMID 22295105, 2012). "Because the EVI1high leukemia cells exhibited an increased adherence to the murine osteoblastic cell line MC3T3-E1 we examined whether this adhesion was dependent on ITGA6 or ITGB4 expression by treating with a neutralizing antibody." (PMID 22295105, 2012). "Concordantly, the expression of surface proteins (CX3CR1, CXCR4, EMB, ITGB4, LSP, VCAM1) important for leukemia infiltration was downregulated in IGFBP2-null bone marrow AML cells." (PMID 24191913, 2013). "Two EVI1low (K562 and U937) and three EVI1high (UCSD/AML1, PT9 and PT11) leukemia cell lines were co-cultured with MC3T3-E1 cells, and the mixed cultures were subsequently treated with anti-ITGA6 or anti-ITGB4 antibody or the control isotype anti-rabbit IgG." (PMID 22295105, 2012). "We found that the EVI1high leukemia cells with increased ITGA6 and ITGB4 expression exhibited stronger adhesion to laminin complexes than the EVI1low leukemia cells; although, the EVI1low leukemia cells exhibited increased adhesion to fibronectin." (PMID 22295105, 2012). "Taken together, the results demonstrated that ITGB4, ITGA6, ITGA9, and VE-cadherin are the candidate integrin genes with increased adhesion ability in EVI1high leukemia cells." (PMID 22295105, 2012). "We found that the adhesion ability of EVI1high leukemia cells to laminin increased with the increased expression of ITGA6 and integrin β4 (ITGB4)." (PMID 22295105, 2012). "The introduction of small-hairpin RNA against EVI1 (shEVI1) into EVI1high leukemia cells reduced the cell adhesion ability and downregulated the expression of ITGA6 and ITGB4." (PMID 22295105, 2012). "ITGB1 and ITGA4 were expressed as very late antigen-4 (VLA-4) in most of the cell lines, but ITGB4 and ITGA6 were expressed in all three leukemia cell lines and in the two primary EVI1high leukemia cell lines." (PMID 22295105, 2012). "In addition, the overexpression of EVI1 in EVI1low leukemia cells enhanced their cell adhesion ability and increased the expression of ITGA6 and ITGB4." (PMID 22295105, 2012). "The ability of the three EVI1high leukemia cells to bind to MC3T3-E1 cells was significantly reduced upon treatment with anti-ITGA6 or anti-ITGB4 antibody, whereas the binding ability of the two EVI1low leukemia cells did not change." (PMID 22295105, 2012).
leukemia (continued). "Two days after treatment, the binding activity of all four cell lines was significantly reduced by the treatment with anti-ITGA6 or anti-ITGB4 antibodies; however, isotype IgG, anti-ITGB2 or anti-ITGB3 antibodies did not inhibit the binding of EVI1high leukemia cells to matrigel." (PMID 22295105, 2012). "Two leukemia (UCSD/AML1 and MOLM1) and two primary human AML (PT9 and PT11) cells lines were cultured on matrigel and treated with or without anti-ITGA6, ITGB2, ITGB3, or ITGB4 antibodies." (PMID 22295105, 2012).
nasopharyngeal carcinoma (2 papers, 2021 to 2025). A carcinoma arising from the nasopharyngeal epithelium. "Notably, NAT10 extends its regulatory reach beyond protein-coding RNAs—ac4C modification of lncRNA SIMALR enhances its stability, enabling activation of eEF1 A2-mediated ITGB4/ITGA6 translation in nasopharyngeal carcinoma." (PMID 40588654, 2025).
ovarian tumor (2 papers, 2024 to 2025). "Furthermore, our gene ontology analysis of ovarian tumor samples with high ITGB4 expression highlighted several critical cellular mechanisms being influenced." (PMID 40361400, 2025). "GSE133859 provided paired OC samples, which demonstrated that ITGB3, ITGB4, ITGB7, and ITGB8 increased in ovarian tumor tissue compared with normal tissue." (PMID 38814534, 2024).
schizophrenia (2 papers, 2018 to 2023). A major psychotic disorder characterized by abnormalities in the perception or expression of reality. "Exome sequence data from the UK10K project was used to identify three rare, amino acid changing variants in the ITGB4 gene which segregated with schizophrenia in two families: rs750367954, rs147480547 and rs145976111." (PMID 29526452, 2018). "Further support comes from data from 872 subjects from the Western Australian Family Study of Schizophrenia and 36,355 controls who reported two SCZ case only ITGB4 variants." (PMID 29526452, 2018).
serous ovarian cancer (2 papers, 2023 to 2024). "TNMplot revealed that, in serous ovarian cancer (SOC) tissues, both YKL40 and ITGB4 were significantly upregulated in tumor tissues compared with normal tissues." (PMID 39408927, 2024).
squamous cell carcinoma (2 papers, 2023 to 2025). A carcinoma arising from squamous epithelial cells. "A comprehensive study on esophagus squamous cell carcinoma distinguished the expression pattern of ITGB4 into pathological and physiological states." (PMID 37371594, 2023).
Allergy (1 paper, 2012). An allergy is an immune response or reaction to substances that are usually not harmful. "Given that the PD-1 ligation delivered an inhibitory signal to T cell activity, the upregulation of B7H1 and B7DC after ITGB4 silencing may be associated with T cells proliferation and derivation after allergy exposure." (PMID 22545078, 2012).
aneurysm (1 paper, 2024). Bulging or ballooning in an area of an artery secondary to arterial wall weakening. "In the GEO157628 dataset, ITGB4 was significantly increased in 11 patients with MMD compared with six patients with aneurysm as controls." (PMID 38628905, 2024).
Anxiety (1 paper, 2018). Intense feelings of nervousness, tension, or panic often arise in response to interpersonal stresses. "ITGB4−/− mice exhibited mania-like behavior, including hyperlocomotion, d-amphetamine-induced hyperactivity, and reduced anxiety-like behavior." (PMID 30170608, 2018).
bone metastasis (1 paper, 2021). Transfer of a neoplasm from its primary site to bones. "SMOX-58,619-AP (p = 0.015), INO80C-45,170-AP (p = 0.022) and ITGB4-43,489-ES (p = 0.048) were found to be significantly related to both bone metastasis and OS in the Venn plot." (PMID 34402716, 2021).
breast tumors (1 paper, 2019). "Single-cell transcriptome analysis of non-tumor cells isolated from primary breast tumors revealed that TAMs expressed high levels of ITGB4, compared with other non-tumor cells within the tumor microenvironment." (PMID 31091437, 2019).
bronchopulmonary dysplasia (1 paper, 2023). Bronchopulmonary dysplasia is a chronic respiratory disease that results from complications related to lung injury during the treatment of infant acute respiratory distress syndrome in low-birth-weight premature infants or from abnormal lung development in older infants. "In this study, we characterized the role of ITGB4 deficiency in bronchopulmonary dysplasia (BPD)." (PMID 37698050, 2023).
Burkitt lymphoma (1 paper, 2021). A rare form of malignant mature B-cell non-Hodgkin lymphoma. "For Family 3 (Burkitt’s lymphoma), TNNT3, SIRPB1, TRMT1, ITGB4, and DCHS1 were the top-five ranked genes." (PMID 34624066, 2021).
cystic fibrosis (1 paper, 2023). Autosomal recessive disorder caused by pathogenic variants in the CFTR gene (cystic fibrosis transmembrane conductance regulator), which encodes a chloride and bicarbonate channel expressed in epithelial cells, and follow the diagnosis criteria. "Eight participants (0.93%) had a carrier status and heterozygous P/LP variants for AR diseases: CFTR cystic fibrosis, ITGB4 junctional epidermolysis bullosa type 5A, MEFV AR familial Mediterranean fever, and SLC7A9 AR cystinuria." (PMID 36635046, 2023).
dysplasia (1 paper, 2023). A usually neoplastic transformation of the cell, associated with altered architectural tissue patterns. "In accordance with these published studies, we found ITGB4 expression to be significantly elevated in postoperative OSCC tissues when compared with normal oral mucosa or dysplasia." (PMID 37371594, 2023).
endometriosis (1 paper, 2022). The growth of functional endometrial tissue in anatomic sites outside the uterine body. "Although the dysregulation of several Integrin subunits has been observed in endometriosis, our results show, in a complementary way, that the integrin beta-4 (ITGB4) receptor for laminin and integrin alpha-IIb (ITGA2B) were upregulated in the eutopic endometrium of women with endometriosis." (PMID 35204508, 2022).
ependymoma (1 paper, 2023). A WHO grade II, slow growing tumor of children and young adults, usually located intraventricularly. "Gene expression analysis indicates that transcription of integrin β4 (ITGB4), but not β1 (ITGB1), is significantly up-regulated in PFA compared to ZFTA ependymoma and normal brain samples, suggesting that the integrin α6β4 heterodimer is the functional form relevant for PFA tumors." (PMID 37085539, 2023).
focal segmental glomerulosclerosis (1 paper, 2021). A renal disorder characterized by sclerotic lesions in the glomeruli. "Focal segmental glomerulosclerosis and CAKUT were described in junctional EB with ITGB6 and ITGB4 mutations leading to abnormal integrin β6 and β4 subunits." (PMID 34123558, 2021).
Glucose intolerance (1 paper, 2026). Glucose intolerance (GI) can be defined as dysglycemia that comprises both prediabetes and diabetes. "The predictor variables can be considered in three groups: those with insulin and glucose intolerance (Mbd2, Tnip1, Itgb4, and Iffo2), those with BMR (1010001N08RiK and Clvs2), and those associated with Tb (Calb2)." (PMID 41432313, 2026). "Similarly Itgb4 and Iffo2 DNAm correlate with glucose intolerance with Itgb4 upregulated in diabetic glomeruli and Iffo2 methylation associated with dietary glycaemic load." (PMID 41432313, 2026).
hemorrhage (1 paper, 2024). Loss of blood from the vascular compartment to the exterior or into nonvascular body space as a result of rupture or severance of the blood vessels. "In conclusion, our study suggests that glutamine may be an independent risk factor for hemorrhage or infarction in patients with MMD and targeting ITGB4 could potentially be therapeutic approaches for MMD." (PMID 38628905, 2024).
kidney cancer (1 paper, 2018). Primary or metastatic malignant neoplasm involving the kidney. "Our study identified that the expression of CD151 downstream genes ITGB1, ITGB4, and PLEC may have additional prognostic values in kidney cancers." (PMID 29843367, 2018).
lymphoma (1 paper, 2022). A malignant (clonal) proliferation of B- lymphocytes or T- lymphocytes which involves the lymph nodes, bone marrow and/or extranodal sites. "Integrins elevated in the lymphoma group through our study included: α1, α5, α6, α7 and β4 (ITGB4)." (PMID 36295095, 2022).
metastatic prostate carcinoma (1 paper, 2021). A carcinoma that arises from the prostate gland and has spread to other anatomic sites. "Among the eight integrin subunits analyzed, ITGA5, ITGAV, ITGB1, ITGB3, ITGB4, and ITGB5 were upregulated in the bone compared with the other organs, suggesting that some integrins may confer osteotropic properties on metastatic prostate cancer." (PMID 33514011, 2021).
Nephropathy (1 paper, 2023). A nonspecific term referring to disease or damage of the kidneys. "Eight heterozygous variants were identified in nephropathy-associated genes (CLCN2, C5orf42, GSN, LMX1B, CEP164, PKD1, ITGB4, and KANK2), but each could be discounted having been inherited from an unaffected parent." (PMID 37148394, 2023).
oral cancer (1 paper, 2024). "Quantitative real-time PCR analysis has identified a high ITGB4/JUP ratio as a significant factor promoting distant metastasis in oral cancer." (PMID 39169946, 2024).
rectal tumors (1 paper, 2022). "The distribution of ITGB4 showed higher expression in right‐sided tumors as compared to left‐sided and rectal tumors and ZO‐1 showed higher expression in rectal tumors as compared to left‐sided and right‐sided tumors." (PMID 34890102, 2022).
respiratory failure (1 paper, 2022). The significant impairment of gas exchange within the lungs resulting in hypoxia, hypercarbia, or both, to the extent that organ tissue perfusion is severely compromised. "PT25 with LAMA3 mutations and PT24 with ITGB4 mutations expired within a few months after birth from sepsis and respiratory failure." (PMID 36578049, 2022).
Rett syndrome (1 paper, 2025). A severe neurodevelopmental disorder affecting the central nervous system. "We further highlight disorder-associated alterations, including upregulation of ITGB4 across Rett syndrome datasets." (PMID 40500308, 2025).
rheumatoid arthritis (1 paper, 2020). A chronic, systemic autoimmune disorder characterized by inflammation in the synovial membranes and articular surfaces. "The only ITGB4 directly targeted drug R1295 was still under investigation for the treatment of rheumatoid arthritis." (PMID 32765584, 2020).
Stroke (1 paper, 2024). Sudden impairment of blood flow to a part of the brain due to occlusion or rupture of an artery to the brain. "Further, ITGB4 represents a potential biomarker reflecting stroke risk in patients with MMD." (PMID 38628905, 2024). "We detected the protein level of ITGB4 using immunofluorescence staining and found higher ITGB4 levels in patients with stroke." (PMID 38628905, 2024). "In the present study, we suggest that glutamine induces the EndMT via ITGB4 and the MAPK–ERK/Smad pathway, being associated with an independently increased risk of stroke in patients with MMD." (PMID 38628905, 2024). "ITGB4 was significantly increased in MMD patients with stroke (p < 0.05)." (PMID 38628905, 2024).
teratoma (1 paper, 2024). A non-seminomatous germ cell tumor characterized by the presence of various tissues which correspond to the different germinal layers (endoderm, mesoderm, and ectoderm). "In combination with absence of ITGB4 in iPS cells, which is necessary for adhesion to the BMZ32,33, we predicted the likelihood of teratoma formation to be low." (PMID 38992003, 2024).
thyroid carcinomas (1 paper, 2012). "The expression of the ITGA6/ITGB4 complex could promote tumor progression and the metastasis of various cancer cells, including breast, colorectal, and thyroid carcinomas." (PMID 22295105, 2012).
urothelial carcinoma (1 paper, 2021). A malignant neoplasm derived from the transitional epithelium of the urinary tract (urinary bladder, ureter, urethra, or renal pelvis). "Expression of JUP in normal urothelial tissue and urothelial carcinoma, ITGB4 in normal urothelial tissue and urothelial carcinoma were also shown." (PMID 34402716, 2021).